INS (insulin)
Diseases named in the same sentence as INS in open-access papers (continued):
Sharing a sentence is not in itself a finding about the gene and the disease.
Hyperglycemia (continued). "Pasireotide-associated hyperglycemia is related to reduced insulin secretion and incretin hormone responses, without changes in hepatic/peripheral insulin sensitivity." (PMID 26918140, 2015). "Additionally, finger stick glucose monitoring should be completed every 4 to 6 hours in any patient who is nil per os (NPO), with supplemental insulin used to correct hyperglycemia back to normal values." (PMID 26078998, 2015). "However, treating diet induced obese rats with a low dose of streptozotocin damages insulin producing β-cells so that hyperglycemia develops even though insulin levels are similar or even higher than in normal fed control rats." (PMID 26229968, 2015). "However thyroid hormone has also been reported to ameliorate hyperglycemia and hyperinsulinemia when administered to a severely insulin resistant patient." (PMID 25849936, 2015). "In this study, an economical method was established to prepare large amounts of DNJ, and the data presented in this paper demonstrated that DNJ alleviated hyperglycemia by improving insulin sensitivity via activating insulin signaling PI3K/AKT pathway in skeletal muscle of db/db mice." (PMID 26690098, 2015). "Similarly, rapamycin treatment to normoglycemic, pre-diabetic P. obesus treated with rapamycin display heightened hyperglycemia and increased insulin resistance in part by reducing pancreatic β-cell function." (PMID 26568298, 2015). "Adverse outcomes in surgical patients may be due to hyperglycemia, and insulin therapy in the ICU has yielded diverse outcomes." (PMID 25670921, 2015). "Diabetic rats exhibited hyperglycemia (22.3 ± 2.19 mmol/L vs. 8.2 ± 0.94 mmol/L, P < 0.05), decreased body weight gain (286.6 ± 14.61 g vs. 419.7 ± 12.25 g, P < 0.05) and reduced insulin levels (0.51 ± 0.093 ng/mL vs. 2.42 ± 0.466 ng/mL, P < 0.05) compared with CON group." (PMID 25887435, 2015). "The neonate was treated with intravenous insulin, obtaining a slight control of hyperglycemia." (PMID 26576310, 2015). "Recently, a 12-week supplementation with dieckol-rich extract (1500 mg per day) from Ecklonia cava in a randomised, double-blind, placebo-controlled clinical trial involving 80 pre-diabetic individuals demonstrated significant reduction of insulin resistance and post-prandial hyperglycaemia." (PMID 26308010, 2015). "The severity of this hyperglycaemia is correlated to mortality and morbidity in such patients, and normoglycaemia obtained by insulin infusion may reduce mortality and morbidity." (PMID 26567860, 2015). "Additionally, hyperglycaemia induces insulin secretion, which can increase the preload of the heart and decrease cardiac output." (PMID 26392171, 2015). "The second phase likely represents insulin synthesis and secretion in response to hyperglycemia." (PMID 25841258, 2015). "This response prevents TNF-α from interfering in insulin signalling and may prevent hyperglycaemia and metabolic disorder." (PMID 26512338, 2015). "Thus, in patients with impaired glucose tolerance and in diabetic patients with mild fasting hyperglycemia (6.1–7.8 mM), plasma insulin response to glucose is uniformly increased." (PMID 26555895, 2015). "Recent studies in healthy volunteers showed that hyperglycemia associated with pasireotide treatment results from a decrease in incretin and insulin secretion, with no change in insulin sensitivity." (PMID 25537481, 2015). "Second, persistent hyperglycemia observed in critically ill patients is basically not caused by continuous glucose administration but by endogenous alterations such as resistance to insulin." (PMID 26207186, 2015). "At this stage, whether an insulin-resistant individual will progress to frank hyperglycemia depends on the ability of islets to provide adequate compensatory insulin secretion." (PMID 25811804, 2015).
Hyperglycemia (continued). "Currently, we know that a diet rich in saturated fatty acids might lead to changes in the action of insulin, with hyperglycemia, increased body mass, and a systemic proinflammatory state, which can be transmitted to other generations." (PMID 25880318, 2015). "Insulin is used worldwide for treatment of hyperglycemia in patients with severe TBI." (PMID 25822252, 2015). "Furthermore, plasma β-amyloid (40/42) levels are increased in Alzheimer’s disease patients with hyperglycemia and they exacerbate hepatic insulin resistance by activating Janus kinase-2 signaling in the liver." (PMID 25755673, 2015). "Further, long-term experiments are required to determine whether the cells continue to secrete insulin over a more extended period than the 150 days studied here and whether their control of hyperglycemia improves with time." (PMID 25629318, 2015). "However, a great vascularization of islets is associated with macrophage infiltration and proinflammatory cytokine production, resulting in impaired insulin secretion, a decrease in the beta cell mass, and hyperglycemia." (PMID 26175757, 2015). "A deficiency in Cr may result in glucose intolerance, elevated circulating insulin, fasting hyperglycemia, and even impair growth." (PMID 25971249, 2015). "Indeed, prolonged hyperglycemia, with concomitant higher demands for insulin secretion, leads to a decrease in Gjd2 expression (which codes for Connexin36 gap junction channels) in mice." (PMID 26266953, 2015). "Much evidence implicates insulin resistance (ie, when a defined concentration of insulin does not effect a predictable metabolic response) and hyperglycaemia as the mechanism by which maternal obesity causes excessive neonatal birthweight." (PMID 26165398, 2015). "Impaired insulin signalling could induce glucose transporters (Gluts) diminution, which limits glucose uptake and contributing to the hyperglycemia." (PMID 25658428, 2015). "Thus, after successful kidney transplant, insulin clearance by the kidney improves, unmasking preexisting glucose intolerance to contribute to the hyperglycemia observed in the immediate post-operative setting." (PMID 25721247, 2015). "Therefore, many patients who are initially treated with oral hypoglycemic agents (OHAs) eventually require a treatment strategy that includes insulin to counteract persistent hyperglycemia." (PMID 24684803, 2014). "Hyperglycemia was relentlessly treated with multiple daily insulin injections." (PMID 24428849, 2014). "Following the challenge, hyperglycemia was significantly higher in South East Asian and Chinese participants compared with European Caucasians, while Indians and South East Asians showed a 2-3-fold higher insulin response than Europeans." (PMID 24744783, 2014). "Finally, the higher insulin dose needed by these patients supports the idea that fasting type hyperglycemia patients are more insulin resistant than postprandial type hyperglycemia patients." (PMID 23880900, 2014). "Patients treated with the basal-bolus insulin regimen attained lower fasting blood glucose (10.8±2.3 versus 11.6±3.5 mmol/L; p = 0.028) and mean glucose levels (12.3±1.9 versus 12.8±2.2; p = 0.021) throughout severe or acute hyperglycemia compared with sliding-scale insulin regimens." (PMID 25181406, 2014). "The slight but significantly delayed recovery from hyperglycemia observed in the IH group may indicate that the beta cells after IH treatment become dysfunctional, and that is why the levels of insulin in the IH animals are low." (PMID 24587273, 2014). "Perhaps, a result favoring intensive insulin therapy could have been found to occur if a higher concentration range was used in the intensive insulin group, in comparison with uncontrolled hyperglycemia." (PMID 25136614, 2014).
Hyperglycemia (continued). "All lines exhibited a mild decrease in body weight, but the highest overexpression of miR-184 (∼100-fold in Tg-04 and 32) resulted in severe hyperglycemia and reduced systemic insulin levels, whereas a 5-fold increase (Tg-96) induced glucose intolerance and impaired insulin release." (PMID 24361012, 2014). "In combining pre and post-exercise rapid-acting insulin dose reductions some patients may be exposed to periods of hyperglycaemia." (PMID 24858952, 2014). "As no changes in structure of the perivascular nerve plexus or in peripherin protein expression or immunolabeling were observed in PMAs from STZ-HI rats, the effects observed in PMAs from STZ-LI rats were likely due to hyperglycemia and/or to the reduced neurotrophic action of insulin." (PMID 24847201, 2014). "Moreover, we previously reported that 5-HT induced the elevation of plasma glucose and insulin concentrations through different 5HTRs in mice, and that hyperglycemia after the injection of 5-HT was induced by repressing glucose uptake into the tissues." (PMID 24505376, 2014). "Together, our functional data propose a model where identified candidate genes may contribute to hyperglycemia in T2D patients by both lowering insulin and increasing glucagon secretion from pancreatic islets." (PMID 24603685, 2014). "When fed water with 10% dextrose, however, they had an insulin-deficient response (sustained postprandial hyperglycemia with no insulin)." (PMID 25566195, 2014). "Type 1 diabetes was diagnosed by the onset of hyperglycemia, the absolute dependence on insulin treatment for survival, and by the presence of severe deficiency of insulin secretion (i.e., very low or undetectable fasting C–peptide levels) and of anti-islet cell auto-antibodies." (PMID 24636465, 2014). "If hyperglycemia secondary to pasireotide treatment in patients with Cushing’s disease remains uncontrolled by these combinations, establishing insulin therapy together with maintained metformin treatment may be necessary." (PMID 23564338, 2014). "Thus Rap-treatment significantly advanced DM in ZDF rats because a two-fold reduction of insulin in conditions of severe hyperglycemia is a step that would expedite DM progression." (PMID 25062042, 2014). "Also, a bilberry extract fed to diabetic KK-Ay mice ameliorated hyperglycemia and enhanced insulin sensitivity accompanied by AMPK activation." (PMID 24669315, 2014). "In addition, adenoviral BiP overexpression is able to reduce ER stress and reverse hyperglycemia- and hyperlipidemia- induced insulin synthesis and secretion in vitro." (PMID 25010593, 2014). "A recent study of mice with an activating KATP channel mutation (ΔN30-K185E) also found that hyperglycaemia led to a dramatic loss of insulin content without marked changes in islet cell death or proliferation." (PMID 25145789, 2014). "In the identification of hyperglycemia, the use of FPG, 2-h postload glucose, and HbA1c are associate with distinct patterns of insulin sensitivity and insulin secretion, which could possibly explain these findings." (PMID 25960777, 2014). "Also, the HYP-mice hypoinsulinemia measured by us and others is consistent with the observed hyperglycemia and increased gluconeogenesis particularly given the regulatory link with hypophosphatemia and insulin secretion and sensitivity." (PMID 24839967, 2014). "In particular, it remained to investigate whether hyperglycaemia or the “metabolic memory” would directly affect the viability, function, and insulin sensitivity of these GLP-1 secreting cells." (PMID 24648662, 2014). "Since our data establish a causal relationship and implicate Sirt7 as a regulator of the insulin/IGF pathway, our data may also suggest a role of Sirt7 in hyperglycemia associated with chemoresistance." (PMID 24885964, 2014). "Thus, our observed increased expression of both these genes (ENPP1 and ESP) is consistent with the HYP mice hyperglycemia and altered insulin sensitivity." (PMID 24839967, 2014).
Hyperglycemia (continued). "Male Sprague-Dawley rats treated daily with GC-1 while being placed on a commercial high-fat diet showed a 75% reduction of hepatic triglyceride content, but developed fasting hyperglycemia and hyperinsulinemia due to increased glucose production and diminished hepatic insulin sensitivity." (PMID 25538628, 2014). "Patients treated with the basal-bolus insulin regimen attained lower fasting blood glucose (10.8±2.3 versus 11.6±3.5 mmol/L; p = 0.028) and mean glucose levels throughout severe/acute hyperglycemia (12.3±1.9 versus 12.8±2.2; p = 0.021) compared with sliding-scale insulin regimens." (PMID 25181406, 2014). "Incretins, such as glucagon-like peptide-1 (GLP-1) analogues and GLP-1/DPP4-peptidase inhibitors, can increase meal-related insulin secretion without increasing risk for hypoglycemia, and are useful for diminishing hyperglycemia." (PMID 26237474, 2014). "Rapid-acting insulin analogs such as insulin aspart, insulin lispro and insulin gluligine are used to control postprandial hyperglycemia, although the use of prandial insulin results in a higher risk of hypoglycemia and weight gain compared with the use of basal insulin." (PMID 25314300, 2014). "Early biological measurements such as insulin levels and glucose levels during routine medical care or early in pregnancy would be informative in determining hyperglycemia, hyperinsulinemia, or some other metabolic abnormalities for detection of high risk pregnancies." (PMID 25562026, 2014). "Mechanistic studies in healthy volunteers suggest that pasireotide-associated hyperglycemia is due to reduced secretion of glucagon-like peptide (GLP)-1, glucose-dependent insulinotropic polypeptide, and insulin; however, it is associated with intact postprandial glucagon secretion." (PMID 23564338, 2014). "In brief, the suppression of miR-29 expression by insulin could be a previously unidentified cardioprotective mechanism in hyperglycemia." (PMID 25062042, 2014). "Furthermore, SC-derived insulin-producing cells are capable of engrafting and reversing hyperglycemia in mice." (PMID 25009980, 2014). "This hyperglycemia stimulates insulin release and inhibits glucagon liberation." (PMID 25250626, 2014). "For example, insulin resistance of muscle cells leads to hyperglycemia in a T2D patient." (PMID 25334061, 2014). "In spite of this, APM resulted in hyperglycemia and an impaired ability to respond to insulin (ITT), which could be due to enhanced gluconeogenesis fueled by production of the SCFA propionate by the gut microbiota." (PMID 25313461, 2014). "On the other hand, subjects with fasting type hyperglycemia might benefit relatively more from bedtime NPH insulin as its action is strong in the early morning hours." (PMID 23880900, 2014). "Moreover, these differentiated insulin-producing cells were able to alleviate hyperglycemia after being transplanted into diabetic NOD mice." (PMID 25364723, 2014). "Also, patients with primary hyperparathyroidism have impaired glucose-tolerance, hyperglycemia and reduced insulin sensitivity." (PMID 24839967, 2014). "However, further research on how pasireotide influences insulin biosynthesis and secretion, and insulin sensitivity in patients with Cushing’s disease will help to define the optimum treatment strategies for hyperglycemia in this difficult to manage condition." (PMID 23564338, 2014). "In addition, we will explore the history of insulin treatment on stress-induced hyperglycemia during critical illness and update the present understanding in regard to the ongoing moderate versus intensive insulin treatment debate." (PMID 24899891, 2014). "Further in vivo studies revealed that compound 10 significantly reduced hyperglycemia by increasing levels of serum insulin, total protein, and albumin, while the fasting blood glucose, body weight and food intake were restored much closer to those of normal rats." (PMID 25153871, 2014).
Hyperglycemia (continued). "The hypothesis of the present study was that the effects of a long-acting analog glargine and NPH insulin would be different in patients that have different hyperglycemia types." (PMID 23880900, 2014). "In addition to controlling hyperglycemia, cotreatment with MK-0626 recovered pancreatic islet size and the immunoreactivity of insulin in islets compared with TAC treatment." (PMID 24959755, 2014). "The administration of a large dose of insulin, by way of IR-caused stress hyperglycemia control after serious injury, reverses the negative nitrogen balance, promotes tissue healing and reduces the incidence rate of infections and the fatality rate." (PMID 24944612, 2014). "In addition to peripheral hyperinsulinemia and hyperglycemia, obese Zucker fa/fa rats displayed higher OB insulin levels than their lean counterparts." (PMID 25278856, 2014). "Therefore any defects in the action or production of insulin will lead to physiological hyperglycaemia of DM." (PMID 25070239, 2014). "Furthermore, rapa treatment in the monogenic obese and diabetic BKS-Leprdb/db strain suggests that insulin sensitivity is increased by rapa despite continued hyperglycemia." (PMID 25473963, 2014). "Also, the use of insulin as a proxy for type 1 diabetes is strong since the treatment of hyperglycemia is the only indication." (PMID 24498320, 2014). "Thus, treatment of severe or acute hyperglycemia secondary to cardiovascular diseases with a basal-bolus insulin regimen is reasonable, where the bolus doses are administered to control the excessive rise of postprandial blood glucose levels." (PMID 25181406, 2014). "Episodes of hyperglycaemia frequently preceded the episodes of hypoglycaemia, even after eradication of circulating anti-insulin antibodies, suggesting that hyperglycaemia may have been attributable to SIR as well as IAS." (PMID 24711924, 2014). "Both hyperglycemia and insulin have profound effects on the function of innate immune cells." (PMID 24899891, 2014). "Taken together, these results suggest that dietary selenate supplementation in db/db mice decreased hyperglycemia by increasing insulin production and secretion; however, long-term hyperinsulinemia eventually led to reduced antioxidant defense capacity, which exacerbated fatty liver degeneration." (PMID 24983750, 2014). "Nonetheless, during chronic hyperglycemia or nutrient excess, β-cells are exposed to high levels of immature insulin accumulated in the ER lumen, which may induce cell death through UPR-related mechanisms." (PMID 25093191, 2014). "Increased insulin levels may contribute to the reduced hyperglycemia and improved body weight in treated diabetic rats." (PMID 25593725, 2014). "This also suggests that extract of Glycyrrhiza can improve insulin sensitivity and hyperglycemia." (PMID 25421245, 2014). "While the effect of capsaicin on energy expenditure remains unclear, it seems to improve hyperglycemia by increasing plasma insulin level." (PMID 25421245, 2014). "It is however heartwarming that a simple majority (66.7%, n = 36) knew that too little insulin could lead to hyperglycemia." (PMID 24397956, 2014). "Since both decreased insulin and increased glucagon secretion from pancreatic islets are known to contribute to hyperglycemia in patients with T2D, we investigated whether the identified candidate genes also affect glucagon secretion in clonal α-cells." (PMID 24603685, 2014). "However, despite hyperglycemia all along the test, the response of glycemia to insulin injection (insulin tolerance test) was similar between both mice, suggesting that FTO overexpression in the liver did not impair peripheral insulin sensitivity." (PMID 24410832, 2014). "Furthermore, the use of SGLT2 inhibitors in addition to insulin therapy in type 1 diabetic patients is conceivable, for example, to improve their glycaemic profile and avoid hyperglycaemia." (PMID 25365416, 2014). "During hyperglycemia, is ERα induced by glucose itself or by insulin?" (PMID 24498408, 2014).